TNFSF13B (TNF superfamily member 13b)
Diseases named in the same sentence as TNFSF13B in open-access papers (continued):
Sharing a sentence is not in itself a finding about the gene and the disease.
COVID-19 (24 papers, 2020 to 2025). A disease caused by infection with severe acute respiratory syndrome coronavirus 2. "Here, HSCT, PSMB9, STAT2, and TNFSF13B were identified as common risk genes of AF and COVID-19 patients." (PMID 38025532, 2023). "By searching for DTGs associated with IRGs shared between COVID-19 and IS, we identified eight DEGs interacting with two known databases of drug targets: JAK2, ORM1, RNASE2, TNFSF13B, CYBB, EIF2AK2, CD79B and CAMP." (PMID 36969251, 2023). "Patients with mild COVID-19 displayed a marked interaction between neutrophil and plasmablasts through BAFF (TNFSF13B) and BAFF receptors (encoded by TNFRSF13C, TNFRSF13B, or TNFRSF17)." (PMID 34548411, 2021). "As for the four common genes from WGCNA modules (HCST, PSMB9, STAT2, TNFSF13B), the HCST showed significant differences between the control/AF group and the healthy/COVID-19 group, while the STAT2 showed significant differences between the healthy and COVID-19 groups." (PMID 38025532, 2023).
Obesity (21 papers, 2013 to 2025). Accumulation of substantial excess body fat. "Data indicate the anti-inflammatory role of high concentrations of sTNF-R1, sTNF-R2, sTNFRSF8, TNFSF13, and TNFSF13B in obesity." (PMID 34572446, 2021).
periodontitis (20 papers, 2018 to 2025). An acute or chronic inflammatory process that affects the tissues that surround and support the teeth. "The TNF receptor family is involved in many of the selected inflammatory diseases, e.g., TNFRSF10B in Osteoporosis, Osteomyelitis and periodontitis, TNFRSF11B and TNFSF13B in Osteopetrosis and Periodontitis, and TNFIP6/8 in Osteomyelitis." (PMID 30497370, 2018). "These pathways included the fibrosis pathway, which may initiate periodontitis and sicca-like symptoms through the upregulation of TNFSF13B, PML and STAT1." (PMID 35236379, 2022).
Arthritis (19 papers, 2008 to 2025). Inflammation of a joint. "TNFSF members, like RANKL, TNFSF13b and TNFSF14, etc., regulate differentiation, maturation and activation of osteoclastogenic cells in the development of osteoporosis caused by estrogen loss, arthritis or bone metastasis." (PMID 31627291, 2019).
Immunodeficiency (16 papers, 2009 to 2025). Failure of the immune system to protect the body adequately from infection, due to the absence or insufficiency of some component process or substance. "Previous studies on TNFSF13B have mostly focused on immune system diseases and hematological malignancies." (PMID 32311223, 2020).
influenza (14 papers, 2011 to 2025). An acute viral infection of the respiratory tract, occurring in isolated cases, in epidemics, or in pandemics; it is caused by serologically different strains of viruses (influenzaviruses) designated A, B, and C, has a 3-day incubation period, and usually lasts for 3 to 10 days. "Genes such as HEATR9, IL4I1, TNFSF13B (BAFF), and PDCD1 (PD-1) are recently implicated in influenza pathogenesis and mucosal defense, thereby signifying the role of the nasal epithelium against influenza infection." (PMID 31461941, 2019).
melanoma (13 papers, 2021 to 2025). A malignant, usually aggressive tumor composed of atypical, neoplastic melanocytes. "The ITRGM signature includes GBP5, HLA-DPB1, XBP1, CD40, CXCL10, and TNFSF13B, each playing pivotal roles in the immune response and tumor microenvironment of melanoma." (PMID 39355255, 2024). "TNFSF13B (APRIL), a proinflammatory cytokine, supports T-cell survival and enhances dendritic cell functions in melanoma and other cancers." (PMID 39355255, 2024). "Interestingly, it was reported that there was a stratification of high and low plasma TNFSF13B in melanoma patients treated with anti-PD1/PDL1 therapy, which again hinted that TNFSF13B shared extensive heterogeneity between patients." (PMID 37443022, 2023). "Overall, 89%, 92%, 82%, and 50% of patients failed to display detectable serum levels of BAFF/TNFSF13B, CX3CL1, LTα, and CCL21 (defined as < 2 pg/ml, < 0.5 pg/ml, < 1 pg/ml and <7 pg/ml for the respective analytes) amongst an initial cohort of 78 melanoma patients evaluated." (PMID 37435077, 2023).
allergic disease (12 papers, 2012 to 2024). An immune response that occurs following re-exposure to an innocuous antigen, and that requires the presence of existing antibodies against that antigen. "Since high total IgE levels is a hallmark of both, helminth infections and allergic diseases, the conservative role of TNFSF13B on this phenotype supports potential evolutionary links between helminth immunity and allergic responses." (PMID 27977724, 2016).
myasthenia gravis (12 papers, 2016 to 2026). Myasthenia gravis (MG) is a rare, clinically heterogeneous, autoimmune disorder of the neuromuscular junction characterized by fatigable weakness of voluntary muscles. "The TNFSF13B variant, resulting in an overexpression of the B cell activating factor (BAFF), was found to be associated with MS and SLE in a genome-wide association study in Sardinia and can help to explain the higher frequencies of myasthenia gravis." (PMID 39703505, 2024).
non-Hodgkin lymphoma (12 papers, 2006 to 2025). Distinct from Hodgkin lymphoma both morphologically and biologically, non-Hodgkin lymphoma (NHL) is characterized by the absence of Reed-Sternberg cells, can occur at any age, and usually presents as a localized or generalized lymphadenopathy associated with fever and weight loss. "Notably, an intron variant and a non-coding transcript variant SNP (rs2582869), which potentially impact TNFSF13B transcript half-life (encoding BAFF), were overrepresented in ER patients, and this same SNP is also associated with the B cell cancer, non-Hodgkins lymphoma (NHL)." (PMID 40557147, 2025).
breast carcinoma (11 papers, 2008 to 2023). "In the present review, we will concentrate on the role of a proliferation-inducing ligand (APRIL, TNFSF13), BAFF (TNFSF13B), and their receptors in cancer, the novel biological therapies targeting this system, their role in breast cancer, and their potential use as therapeutic targets." (PMID 32612943, 2020). "First, by analyzing a large breast cancer study (MetaBRIC study), we found that APRIL (TNFSF13), BAFF (TNFSF13B), and BCMA (TNFRSF17) were expressed in 76% of the studied cohort." (PMID 30131941, 2018). "The three HMMR SNPs that were identified by our pathway-based analysis were missed in the GWAS for CIN, probably because those SNPs did not directly contribute to CIN in breast cancer patients but rather through the expression of TNFSF13B." (PMID 29593529, 2018).
dengue (8 papers, 2011 to 2025). "Moreover, the TNFSF13B gene is associated with B cell activation and also showed an immune response to live attenuated tetravalent dengue vaccine candidates." (PMID 38076406, 2023).
inflammatory bowel disease (8 papers, 2020 to 2024). A spectrum of small and large bowel inflammatory diseases of unknown etiology. "TNFSF13B was significantly associated with “TNF signalling pathway”, “IL-17 signalling pathway”, “Inflammatory bowel disease”, “T cell receptor signalling pathway”, and “Antigen processing and presentation”." (PMID 37587523, 2023). "TNFSF13B can regulate the TNF signalling pathway and possibly trigger inflammatory bowel disease." (PMID 37587523, 2023).
diffuse large B-cell lymphoma (7 papers, 2012 to 2025). "A tight correlation between S100A9 and TNFSF13B was also significant in the diffuse large B cell lymphoma (DLBC) samples, indicating that S100A9 might promote TNFSF13B expression in B cell-derived cells." (PMID 34150664, 2021).
neutropenia (7 papers, 2013 to 2025). A decrease in the number of neutrophils found in the blood. "The mechanism of TNFSF13B expression in association with neutropenia is unclear and needs to be elucidated." (PMID 29593529, 2018). "In summary, utilizing a pathway-based approach for the analysis of GWAS data, we identified additional SNPs in the HMMR gene that were associated with neutropenia and also were correlated with TNFSF13B expression." (PMID 29593529, 2018). "HMMR has not been shown to be involved in the mechanism of treatment related neutropenia and the mechanism for how it might be associated with TNFSF13B expression is unclear and should be further explored." (PMID 29593529, 2018). "The potential role of TNFSF13B is not only activating B-cells but also myeloid cells, a potential mechanism for how changes in expression of this gene might predispose patients to treatment related neutropenia." (PMID 29593529, 2018). "Interestingly, three SNPs, rs299293, rs299313, and rs299314, which were located in the hyaluronan mediated motility receptor (HMMR) gene, were trans-eQTLs for TNFSF13B, one of the “top” hits identified in the original GWAS for neutropenia." (PMID 29593529, 2018).
endometriosis (6 papers, 2019 to 2025). The growth of functional endometrial tissue in anatomic sites outside the uterine body. "Increased TNFSF13B B lymphocyte stimulator protein was identified in serum of endometriosis subjects." (PMID 38844959, 2024). "Interestingly, increases in IL-17A, IL18, TNFSF13B, and TNF signaling have all been previously identified in endometriosis conditions." (PMID 35682747, 2022).
lung disease (6 papers, 2020 to 2025). "TNFSF13B (B cell activating factor) is implicated in pulmonary diseases, promoting B cell maturation and proliferation." (PMID 40463504, 2025).
Crohn disease (5 papers, 2017 to 2025). A gastrointestinal disorder characterized by chronic inflammation involving all layers of the intestinal wall, noncaseating granulomas affecting the intestinal wall and regional lymph nodes, and transmural fibrosis. "Furthermore, the participation of TNFSF13B in the “cytokine-cytokine receptor interaction” cell route reveals other diseases in which gene impairment such as Crohn's disease, DM-I, intestinal inflammatory disease, ulcerative colitis, and juvenile idiopathic arthritis could participate." (PMID 31772502, 2019).
periodontal disease (5 papers, 2019 to 2025). "Among the 92 inflammation-related genes evaluated using the TaqManTM Array Plate Human Inflammation Kit (Thermo Fisher Scientific, Waltham, MA, USA), four genes (TNFSF13B, ITGB2, ANXA5, and ANXA3) showed significant differential expression in patients with active periodontal disease." (PMID 40004451, 2025).
follicular lymphoma (4 papers, 2009 to 2025). Follicular lymphoma is a form of non-Hodgkin lymphoma characterized by a proliferation of B cells whose nodular structure of follicular architecture is preserved. "Other notable subtype-specific associations include FAS and follicular lymphoma (minP = 0.006) and TNFSF13B and CLL/SLL (minP = 0.001)." (PMID 19390683, 2009).
preeclampsia (3 papers, 2010 to 2019). Preeclampsia is a hypertensive disorder of pregnancy that is characterized by new-onset hypertension with proteinuria presenting after 20 weeks of gestation, and depending on mild or severe forms may initially present with severe headache, visual disturbances, and hyperreflexia. "We discuss a possible role for TNFSF13B in preeclampsia pathogenesis, and propose the rs16972194 variant as a candidate for further functional evaluation." (PMID 20927378, 2010). "The current study aimed to identify potential functional and structural variants in the positional candidate gene TNFSF13B under the 13q linkage peak and assess their association status with maternal preeclampsia genetic susceptibility." (PMID 20927378, 2010). "Our observation supports TNFSF13B as a potential preeclampsia susceptibility gene in a region of known genetic linkage, and adds evidence to its importance for a successful human pregnancy." (PMID 20927378, 2010). "In conclusion, we observe borderline association between three rare TNFSF13B SNPs, one of which exhibits putative functional characteristics, and maternal preeclampsia genetic susceptibility in our Aust/NZ families." (PMID 20927378, 2010). "We report borderline association to a putative functional SNP within the proximal promoter region of TNFSF13B with preeclampsia susceptibility in affected Aust/NZ families." (PMID 20927378, 2010). "It is therefore tempting to speculate, that disturbed TLR signaling might be one mechanism by which aberrant TNFSF13B regulation could confer susceptibility to preeclampsia." (PMID 20927378, 2010). "Therefore, we present a borderline association for three TNFSF13B SNPs with preeclampsia susceptibility in the Aust/NZ families with the QTDT statistic." (PMID 20927378, 2010). "Our observations support TNFSF13B as a potential novel preeclampsia susceptibility gene." (PMID 20927378, 2010). "The rare TNFSF13B variants exhibiting borderline association with preeclampsia susceptibility in the Aust/NZ families were not replicated in the Norwegian population sample." (PMID 20927378, 2010).
bronchiectasis (2 papers, 2020 to 2021). Segmental, irreversible dilation of the bronchial tree resulting in the accumulation of secretions which leads to obstruction. "A recent study identified different inflammation profiles when comparing gingival tissues of bronchiectasis patients having chronic periodontitis, with 7 genes significantly altered in bronchiectasis patients (LTA, LTB, TNFSF4, TNFSF11, TNFSF13, TNFSF13B, and TNFRSF11B)." (PMID 34765263, 2021).
Down syndrome (2 papers, 2019 to 2023). "The rest have a different cytogenetic location (TNFSF13B on chromosome 13, whilst ANXA3 and ANXA5 on chromosome 4), which seems to corroborate that Down Syndrome causes impairments to the complete genome." (PMID 31772502, 2019).
metastatic disease (2 papers, 2013 to 2023). "Moreover, GSEA analysis revealed that VEGF signaling pathway was significantly enriched in TNFSF13B‐higher tumors, and pan‐cancer analysis manifested that expression of HOOK1 was widely elevated in many cancers and metastatic tumors." (PMID 37085921, 2023).
ZIKV infection (2 papers, 2017). "As a result, only a few DE PCGs involved in immune response, such as TNFSF13B and RIPK2, were upregulated by ZIKV infection." (PMID 29116029, 2017).
Apathy (1 paper, 2023). Apathy is a quantitative reduction of interest, motivation and the initiation and persistence of goal-directed behavior, where often the accompanying emotions, thoughts, and social interactions are also diminished. "After FDR correction, a significant association (FDR corrected p < 0.05) between BAFF/TNFSF13B levels and FBI apathy still existed." (PMID 36890594, 2023). "Notably, BAFF/TNFSF13B was correlated with apathy after stringent correction, a key symptom of bvFTD, suggesting the significant role of the TNF family in disease pathogenesis." (PMID 36890594, 2023). "Plasma levels of BAFF/TNFSF13B were negatively correlated with MMSE scores and positively correlated with FBI apathy and FBI total scores." (PMID 36890594, 2023). "Levels of BAFF/TNFSF13B (β = 0.5269, p < 0.001) were positively correlated with FBI apathy scores (R2 = 0.3872, p = 0.0048)." (PMID 36890594, 2023).
avian influenza (1 paper, 2020). Infection of domestic and wild fowl and other birds with influenza A virus. "One receptor for TNFSF13B, TNFRSF13B, was among the genes significant in the trachea challenge by line interaction at 6 dpi and was differentially expressed between the Fayoumi and Leghorn chickens in the lung in both non-challenged birds and birds challenged with avian influenza." (PMID 32117434, 2020).
bladder cancer (1 paper, 2024). "The results showed that in bladder cancer, FLT3LG not only exhibited significant positive correlations with immune checkpoints (CTLA416, IDO117), cytokines and chemokines (TNFSF13B, TNFRSF14, CXCR3, CCL4) but also exhibited the closest association with genes related to HLA18." (PMID 38213738, 2024).
Brain atrophy (1 paper, 2023). Partial or complete wasting (loss) of brain tissue that was once present. "A relevant study revealed that plasma levels of peripheral inflammatory markers, such as BAFF/TNFSF13B, IL-4, IL-6, IL-17A, and TNF-α, exhibited associations with patterns of brain atrophy, brain hypometabolism, and clinical measures of disease severity and functional status in bvFTD." (PMID 37762113, 2023).
bronchiolitis (1 paper, 2021). Inflammation of the bronchioles characterized by swelling of the bronchioles and mucus accumulation. "In conclusion, signatures of RSV-associated bronchiolitis have been found in this study, including dominance of Haemophilus and a high concentration of BAFF/TNFSF13B, IL-8 and sTNF.R1 in nasal samples, and a high fecal concentration of BAFF/TNFSF13B." (PMID 34140944, 2021). "The concentration of BAFF/TNFSF13B was also significantly higher in fecal samples from the bronchiolitis group." (PMID 34140944, 2021). "In conclusion, the results of this study confirm that RSV-associated bronchiolitis is correlated with an abundance of Haemophilus sequences and to an increase in the concentrations of BAFF/TNFSF13B and IL8 in nasal samples." (PMID 34140944, 2021). "BAFF/TNFSF13B was detected in almost all fecal samples but the concentration in the bronchiolitis group was approximately double that in healthy infants, similarly to nasal samples." (PMID 34140944, 2021). "Significant differences were obtained between bronchiolitis and control groups for both the frequency of detection and concentration of BAFF/TNFSF13B and sTNF.R1 in nasal samples." (PMID 34140944, 2021). "In relation to the immunological profiles, the concentration of BAFF/TNFSF13B, IL-8, and sTNF.R1 were significant higher in nasal samples from the bronchiolitis group." (PMID 34140944, 2021). "In addition, the concentrations of BAFF/TNFSF13B and sTNF-R1 were also higher in the bronchiolitis group (Wilcoxon rank sum tests, p < 0.010)." (PMID 34140944, 2021).
mesothelioma (1 paper, 2012). A usually malignant and aggressive neoplasm of the mesothelium which is often associated with exposure to asbestos. "We show in this work that MMP2, BAFF/BLyS/TNFSF13B, RANTES/CCL5 and TNFAIP6/TSG-6 are highly expressed in 3D mesothelioma but not in monolayers." (PMID 22737246, 2012).
renal cell carcinoma (1 paper, 2023). "Together, our results demonstrated that the HOOK1 governed TNFSF13B stability and played a critical role in disease progression in renal cell carcinoma." (PMID 37085921, 2023).
seminoma (1 paper, 2024). A radiosensitive malignant germ cell tumor found in the testis (especially undescended), and extragonadal sites (anterior mediastinum and pineal gland). "In the tumor microenvironment of non-metastatic non-seminomas, TNFSF13B was highly expressed on FDC, cDC1 and cDC2 and promoted the proliferation through the receptors TNFRSF13B and TNFRSF17." (PMID 39528470, 2024).
systemic mastocytosis (1 paper, 2024). Systemic mastocytosis (SM) comprises a heterogeneous group of rare acquired and chronic hematological malignancies that are related to an abnormal proliferation of mast cells in tissue, including bone marrow, with or without skin involvement. "Up to 29 proteins were associated with distinct severe activity in patients with systemic mastocytosis (ISM versus AdvSM), including IL-1 receptor type 1 (IL-1RT1) and tumor necrosis factor ligand superfamily member 13B (TNFSF13B) (q < 0.01)." (PMID 38925457, 2024).